ENSG00000222095
Synonyms: LOC124903422
Gene: Small nucleolar RNA gene on chromosome 14 (100,994,257 to 100,994,330, forward strand). Ensembl gene ENSG00000222095.
Gene Ontology:
Biological process: RNA processing
Cellular component: nucleolus
Homologues: Paralogues in human: SNORD114-3 (73% identical), SNORD114-1 (72% identical), SNORD114-11 (72% identical), SNORD114-12 (72% identical), SNORD114-2 (72% identical), SNORD114-14 (70% identical), SNORD114-4 (70% identical), SNORD114-15 (68% identical), SNORD114-17 (68% identical), SNORD114-21 (68% identical), SNORD114-31 (68% identical), SNORD114-13 (66% identical), and 27 more.